SELENOH (selenoprotein H)
Description:
May be involved in a redox-related process.
Synonyms: SelH; C11orf31; C17orf10
Tractability: PROTAC: ubiquitination databases record sites on it.
Gene: Protein-coding gene on chromosome 11 (57,741,491 to 57,743,554, forward strand). Ensembl gene ENSG00000211450.
Subcellular location (Human Protein Atlas): Nucleoli; Nucleoplasm
Gene Ontology:
Molecular function: RNA binding
Cellular component: Golgi apparatus
Genetic constraint (gnomAD): Loss-of-function variants: 9 observed, 7.09 expected, observed/expected ratio (o/e) 1.27, 90% interval 0.75 to 1.88. That is too few expected variants to judge how well the gene tolerates losing a copy. Missense variants: 136 observed, 102.56 expected, observed/expected ratio (o/e) 1.33, 90% interval 1.15 to 1.53. Synonymous variants: 60 observed, 44.35 expected, observed/expected ratio (o/e) 1.35, 90% interval 1.1 to 1.68.
Homologues: Orthologues: chimpanzee SELENOH (98% identical), macaque SELENOH (95% identical), rabbit SELENOH (88% identical), Drosophila melanogaster CG13186 (25% identical), Drosophila melanogaster CG15147 (24% identical).
Diseases named in the same sentence as SELENOH in open-access papers:
SELENOH is named in the same sentence as 14 diseases in open-access papers, as found by Europe PMC text mining. Sharing a sentence is not in itself a finding about the gene and the disease. The quoted sentences say what the papers report.
colorectal cancer (4 papers, 2012 to 2022). A primary or metastatic malignant neoplasm that affects the colon or rectum. "SELENOH KO in vitro and in vivo (on human colorectal cancer cells) unexpectedly increased proliferation and migration, highlighting a role of SELENOH in inhibiting tumour progression and in protecting colorectal cancer cells from uncontrolled proliferation." (PMID 35204134, 2022). "Knock-down of selenoprotein (SELENO)H, for example, triggers proliferation of undifferentiated human HT-29 colorectal carcinoma cells and decreases their differentiation, while SELENOH is significantly downregulated in differentiated HT-29 cells." (PMID 34681720, 2021).
adenoma (1 paper, 2018). A neoplasm arising from the epithelium. "These included increasing down-regulation of GPX3, SELENOP, SELENOS, and SEPHS2 and up-regulation of GPX2, SELENOH, and TXNRD3, in groups of normal-matched tissues, adenomas, and adenomas with HGD." (PMID 30469315, 2018).
lymphoma (1 paper, 2022). A malignant (clonal) proliferation of B- lymphocytes or T- lymphocytes which involves the lymph nodes, bone marrow and/or extranodal sites. "Seven selenoproteins, that included TXNRD1, GPX1, GPX4, SELENOH, SELENOO, SELENOS and SELENOT, were detected in both lymphoma-derived and primary CD4 T cells." (PMID 35163318, 2022).
cancer (6 papers, 2018 to 2024). A tumor composed of atypical neoplastic, often pleomorphic cells that invade other tissues. "These include key biological stress response genes like GPXs, TXNRD3, SELENOS, SELENOH, and the related SOD2 gene implicated in cancer cell survival, and genes such as SELENOP and SEPHS2 involved in Se biosynthesis." (PMID 30469315, 2018). "GPx3 is considered a tumor suppressor, GPx2 seems to act at the very early stages of cancer, while selenoprotein H is a key regulator for the cell cycle, indicating the role of selenoproteins in cancer could be both preventive and therapeutic." (PMID 35682497, 2022). "In this study we have found that isovalerylspiramycin I (ISP I), a novel macrolide antibiotic, suppresses cancer cell growth and tumor metastases by targeting the nucleolar protein selenoprotein H (SELH), which plays critical roles in keeping redox homeostasis and genome stability in cancer cells." (PMID 35387667, 2022). "We have identified its molecular target(s) in cancer cells and found that the active component—ISP I—specifically suppresses selenoprotein H (SELH), a member of a family of selenocysteine-containing proteins." (PMID 35387667, 2022). "In this study, changes in gene expression were observed for SELENOP, SELENOS, and TXNRD3 for all sample groups, while GPX4 was significant in the Irish cancers only and GPX1, SELENOH, and SELENON were differently regulated in the Czech CRCs." (PMID 30469315, 2018). "Additionally, selenoprotein-H was found to play a role in tumorigenesis prevention, and the increased expression we observed in FXSA could also represent one of the protective mechanisms against cancer proposed in individuals with FXS." (PMID 36292679, 2022).
tumor (6 papers, 2018 to 2025). "CAM accelerates the degradation of selenoprotein H, leading to oxidative stress, disrupted ribosomal biogenesis, and apoptosis in tumor cells." (PMID 40778771, 2025). "A further two-group analysis between CR and nCR also demonstrated the overexpression of proteins that play a tumor-suppressive role, including AKAP12, DCTN3, and SELENOH, in the CR group." (PMID 36361712, 2022).
SELENOH also shares sentences with these, for which no sentence is quoted: acute megakaryoblastic leukemia (1 paper); colorectal (1); colorectal tumor (1); glioblastoma (1); melanoma (1); metastatic tumors (1); rectal cancer (1); triple-negative breast carcinoma (1); type 2 diabetes (1).